CYLD (CYLD lysine 63 deubiquitinase)
Diseases named in the same sentence as CYLD in open-access papers (continued):
Sharing a sentence is not in itself a finding about the gene and the disease.
multiple myeloma (22 papers, 2010 to 2025). "Other investigations reveal that inactivated expression of CYLD strongly promotes the Wnt signaling and is associated with a poor prognosis in multiple myelomas and leukemia/lymphoma." (PMID 37549179, 2023). "Somatic mutations affecting CYLD expression beyond the skin were first shown in myeloma, where deletions involving the CYLD locus were associated with poorer clinical outcome." (PMID 37387450, 2023). "On the other hand, the role of CYLD in multiple myeloma depends mainly on the regulation of WNT, as the loss of CYLD leads to pathway hyperactivation and cancer aggressiveness." (PMID 37894364, 2023). "Owing to its role as a deubiquinase, CYLD has been associated with multiple kinds of hematological malignancies, including multiple myeloma, T-cell acute lymphoblastic leukemia (T-ALL), and CLL." (PMID 26950276, 2016). "Our data indicate that increased expression of NFκB regulators have an anti-myeloma effect, and this is supported by the high frequency of inactivating mutations found in these regulators (BIRC3, Traf2/3 and CYLD) in myeloma patients." (PMID 26015393, 2015). "CYLD mutations are associated with constitutive activation of NF-κB in multiple myeloma cells and B cells from mice deficient for wild-type CYLD exhibited constitutive activation of NF-κB." (PMID 23861985, 2013). "Since bortezomib was approved and clinically available for treatment of several malignant tumors, such as multiple myeloma and mantle cell lymphoma, we verified the therapeutic effectiveness of bortezomib treatment for cisplatin resistance caused by CYLD down-regulation in SAS cells." (PMID 31635163, 2019). "In addition, lasting activation of NF-κB due to CYLD mutations has been observed in multiple myeloma." (PMID 29163038, 2017). "Attenuated expression of CYLD is correlated with a poor prognosis in multiple myelomas and leukemia/lymphoma." (PMID 37549179, 2023). "Deletions of NFκB-pathway modulating genes TNFAIP3, BIRC2/BIRC3, TRAF3 or CYLD were identified in 16.6, 4.8, 13.9 and 16.9% of Myeloma XI cases, respectively." (PMID 28584253, 2018). "Homozygous deletions of CYLD and BIRC3 (cIAP2) are found exclusively in multiple myeloma and are both linked to aberrant NF-κB signalling." (PMID 29089486, 2017). "miR-19a is a member of the miR-17-92 cluster and has been shown to be overexpressed in T-cell acute lymphoblastic leukemia and multiple myeloma where it was revealed that miR-19a negatively regulates the expression of CYLD and SOCS-1 respectively to promote cell survival and pathogenesis." (PMID 25886994, 2015). "Given that this is a targeted panel there are no data on other potentially important homozygous deletions in myeloma, such as FAM46C and CYLD both of which have been shown to be biologically or clinically important." (PMID 28234347, 2017). "This suggests that the repressed expression of NFκB inhibitors like A20, CYLD, IκBα and BIRC3 is an important mechanism of myeloma cell survival, and confirms the central role of NFκB signalling in myeloma pathogenesis." (PMID 26015393, 2015). "CYLD is not expressed in multiple myeloma, and inhibits the growth of multiple myeloma by acting on the Dvl substrate." (PMID 33498168, 2021). "No mutations in the CYLD gene were identified in T-ALL patients, indicating that in contrast to the multiple myeloma setting, where CYLD mutations were detected, this gene is inhibited at the transcriptional level." (PMID 24281204, 2010).
breast carcinoma (19 papers, 2016 to 2024). "Downregulation of the cylindromatosis (CYLD) tumor suppressor has been associated with breast cancer development and progression." (PMID 32722292, 2020). "Upregulation of NF-kappaB or JNK activities was observed in specific cases of CYLD-deficient breast cancer cell lines." (PMID 32722292, 2020). "The effects of CYLD deficiency and overexpression in breast cancer cell lines have suggested important tumor suppressive roles." (PMID 32722292, 2020). "Multiple lines of evidence from cell line models and human patient samples have implicated CYLD in breast cancer suppression." (PMID 32722292, 2020). "Our findings explain the association of CYLD downregulation with aggressive breast cancers and lay the ground for the development of targeted therapeutic approaches of CYLD-deficient breast cancers." (PMID 32722292, 2020). "Previous studies detected that downregulation or loss of the CYLD gene in human breast cancers and chronic lymphocytic leukemia and mutations of CYLD caused two clinically distinct cancer syndromes." (PMID 27738385, 2016). "Consequently, they provide a novel conceptual framework that supports and explains a causal implication of deficient CYLD expression in aggressive human breast cancers." (PMID 32722292, 2020). "Interestingly, in one recently published study, analysis of tumor mRNA expression in a specific cohort of breast cancer patients from the TCGA database showed that high expression of CYLD was linked to shorter disease-free survival." (PMID 32722292, 2020). "CYLD inhibits breast cancer growth by negatively modulating the NF-κB pathway and targeting several regulators of NF-κB via deubiquitinase activity." (PMID 34575114, 2021). "MicroRNAs including miR370-3p and miR-301b are identified in vivo to strengthen breast cancer growth through downregulation of CYLD." (PMID 34575114, 2021). "CYLD expression is repressed in breast cancer tissues and functions as an independent prognostic index." (PMID 34575114, 2021). "Patients with high CYLD expression and multiple myeloma, oral squamous cell carcinoma or breast cancer have a better prognosis." (PMID 34179009, 2021). "Studies have also found that the downregulation of CYLD can promote breast cancer metastasis by activating NF-κB." (PMID 34179009, 2021). "It has been reported that CYLD downregulation is an independent factor for poor prognosis in breast cancer and also regulates keratinocyte differentiation and skin cancer progression." (PMID 32708712, 2020). "Downregulation of CYLD expression can augment the viability, migratory capacity, and anchorage-independent growth of basal and luminal human breast cancer cell lines." (PMID 32722292, 2020). "Regarding both Beta1-integrin mediated interactions and LKB1mediated signaling in breast cancer the CYLD (cylindromatosis) protein is of paramount importance too, which act as a deubiquitinating enzyme and is considered as a tumor suppressor." (PMID 31191821, 2019). "In breast cancer, CYLD protein expression levels were lower in tumor than in normal tissues." (PMID 33827598, 2021). "Despite the extensive evidence supporting a tumor-suppressing role of CYLD in breast cancer, one cannot exclude the possibility that CYLD may also play a tumor-promoting role in certain cases of breast cancer." (PMID 32722292, 2020). "Given our observations in vitro and in vivo in mice, we next set out to investigate whether CYLD downregulation correlates with aberrant YAP/TAZ signaling in human breast cancers." (PMID 32722292, 2020). "Furthermore, in human breast cancer samples, downregulation of CYLD expression correlates with enhanced YAP/TAZ-regulated target gene expression." (PMID 32722292, 2020). "In addition, CYLD protein downregulation was correlated with poor prognosis in primary breast cancer patients." (PMID 32722292, 2020). "Loss of CYLD up-regulates NFKB signaling and enhance metastasis in breast cancer." (PMID 31191821, 2019).
breast carcinoma (continued). "Furthermore, it is possible that the role of CYLD in breast cancer development and evolution may depend on the particular type of breast cancer, as well as additional genetic and epigenetic alterations that exist in these tumors." (PMID 32722292, 2020). "IKKε-induced phosphorylation at Ser418 of CYLD decreased its activity and completely blocked CYLD-mediated deubiquitination of TRAF2, thereby promoting tumorigenesis in breast cancer cells." (PMID 34177595, 2021). "For example, IKBKE phosphorylates CYLD and TRAF2 in breast cancer cells, which induces NF-κB activation and contributes to cell transformation." (PMID 34544426, 2021). "The authors mainly focused on the roles of several important DUBs in breast cancer, such as USP9X, USP15, and CYLD(Cylindromatosis tumor suppressor protein)." (PMID 34575114, 2021). "Remarkably, the reciprocally changed levels of OTULIN and HOIP revealed from these small sets of TNBC specimens were also reflected in large cohorts of breast cancer specimens; no significant change in CYLD protein expression was shown." (PMID 35939695, 2022). "Also, CYLD protein was identified both in Beta1-integrin mediated interactions and LKB1 mediated signaling in breast cancer samples." (PMID 31191821, 2019). "In fact, the lack of CYLD function has been detected in many human tumor cells of lung, stomach and breast cancer, in which the activation of NF-κB, JNK and/or c-Myc appears as the mechanisms through which CYLD downregulation promotes tumor development." (PMID 30631004, 2019).
gastric cancer (19 papers, 2014 to 2024). A primary or metastatic malignant neoplasm involving the stomach. "Other studies also reported that CYLD down-regulation caused by microRNA was associated with resistance for either gemcitabine in pancreatic cancer, and cisplatin in gastric cancer." (PMID 36376983, 2022). "A previous study reported that CYLD can be regulated by lncRNA CRAL/miR-505 in human gastric cancer cells to reverse cisplatin resistance." (PMID 34326699, 2021). "miR-362-5p overexpression can facilitate cell proliferation, colony formation, and resistance to cisplatin-induced apoptosis in BGC-823 and SGC-7901 gastric cancer cells via repressing the tumor suppressor CYLD and increasing NF-κB activity." (PMID 31929841, 2019). "miR-362 targeted cylindromatosis (CYLD) activation of the NF-κB pathway induced cell growth and apoptosis tolerance in gastric cancer." (PMID 30155491, 2018). "A later study revealed that miR-425 was also involved in gastric cancer progression and metastasis by suppressing CYLD." (PMID 30285885, 2018). "For proliferation, miR-130b targets CYLD to inhibit proliferation and induces apoptosis in human gastric cancer cells." (PMID 28165066, 2017). "Altogether, our results suggest that miR-362 upregulation activates NF-κB signaling by repressing CYLD, consequently leading to cell proliferation and apoptosis resistance in gastric cancer." (PMID 24495516, 2014). "Our study presents a new possibility for improving the prognosis of gastric cancer patients with the therapeutic effects of miR-362 inhibition through CYLD downregulation and persistent decrease of NF-κB activity." (PMID 24495516, 2014). "In the present study, miR-362 directly targeted CYLD and led to cell proliferation and apoptosis resistance, which we believe is a novel mechanism for reducing CYLD in gastric cancer." (PMID 24495516, 2014). "MiR-362 levels in the 10 freshly collected gastric cancer specimens were inversely correlated with CYLD expression levels (r = -0.796, P < 0.001) but positively correlated with nuclear p65 expression (r = 0.670, P = 0.034)." (PMID 24495516, 2014). "Luciferase assay confirmed that miR-362 directly binds the 3′-UTR of CYLD mRNA and inhibits CYLD translation in gastric cancer cells." (PMID 24495516, 2014). "Expression of the tumor suppressor CYLD was inhibited by miR-362 in gastric cancer cells; miR-362 levels were inversely correlated with CYLD expression in gastric cancer tissue." (PMID 24495516, 2014). "The results suggest that miR-362 plays an important role in repressing the tumor suppressor CYLD and present a novel mechanism of miRNA-mediated NF-κB activation in gastric cancer." (PMID 24495516, 2014). "LncRNA CRAL/miR-505/CYLD/Akt can reverse cisplatin resistance in gastric cancer." (PMID 39605891, 2024). "For example, miR-20a could confer DDP resistance by silencing EGR2 and cylindromatosis (CYLD) in gastric cancer cells." (PMID 32192494, 2020). "MiR-130b targets CYLD to inhibit proliferation and induce apoptosis in human gastric cancer cells." (PMID 28165066, 2017). "Moreover, miR-362 activated NF-κB signaling through directly targeting of the 3′ untranslated region (3′-UTR) and suppression of CYLD in human gastric cancer cells." (PMID 24495516, 2014). "It has been found that CRAL is mainly located in the cytoplasm and sponges the endogenous miR-505, consequently increasing CYLD expression, suppressing AKT activation, and enhancing the sensitivity of gastric cancer cells to DDP in vitro and in vivo." (PMID 32460771, 2020). "Taken together, our results suggest that miR-500 overexpression activates the NF-κB signalling pathway by repressing CYLD, TAX1BP1, and OTUD7B, and consequently results in gastric cancer aggressiveness and poor clinical outcomes." (PMID 25595906, 2015). "Herein, analysis by publicly available algorithms and our serial experimental results demonstrate that CYLD, TAX1BP1, and OTUD7B are bona fide targets of miR-500 in gastric cancer." (PMID 25595906, 2015).
gastric cancer (continued). "Moreover, as CYLD can be transcriptionally induced by the NF-κB pathway in a negative feedback pathway, we may have uncovered a mechanism that leads to persistent NF-κB activation in gastric cancer." (PMID 24495516, 2014). "In contrast, this miRNA inhibits cell proliferation and colony formation and induces apoptosis in gastric cancer by targeting CREB1 and reduces drug resistance in pancreatic cancer by inhibiting CYLD and BCL-2." (PMID 25299073, 2014). "Via sponging endogenous miR-505 to upregulate cylindromatosis (CYLD) expression and subsequently inhibiting AKT activation, ectopic CRAL expression can weaken DDP resistance of gastric cancer cells by potentiating DDP-induced DNA damage and cell apoptosis in vitro and in preclinical models." (PMID 32192494, 2020). "Therefore, our results suggest a novel mechanism of DUB dysregulation involving CYLD, A20, and OTUD7B in gastric cancer and provide a functionally and clinically relevant epigenetic mechanism in cancer progression." (PMID 25595906, 2015). "Lastly, we examined whether miR-500–mediated suppression of CYLD, TAX1BP1, and OTUD7B, and NF-κB activity in gastric cancers are clinically relevant." (PMID 25595906, 2015). "It emerged that CRAL could function as a ceRNA for endogenous miR-505, thereby upregulating expression of cylindromatosis (CYLD), which, in turn, suppressed AKT activation and enhanced the sensitivity of gastric cancer cells to cisplatin via the miR-505/CYLD/AKT axis." (PMID 35089117, 2022).
skin tumors (19 papers, 2011 to 2025). "Almost all CCS skin tumours exhibit loss of heterozygosity affecting chromosome 16q12-13, the CYLD locus." (PMID 37387450, 2023). "CYLD has been implicated in the pathogenesis of many malignancies, including breast, colon, liver and skin cancers." (PMID 36922488, 2023). "Low-level CYLD expression was also associated with poor patient survival in oral squamous cell carcinoma and inactivating CYLD mutations can promote skin tumor progression." (PMID 32708712, 2020). "We investigated Notch pathway activity in skin tumours from patients with germline mutations in CYLD and found that JAG2 protein levels and Notch target genes were upregulated." (PMID 25565632, 2014). "The CYLD defective tumours described here provide a human skin tumour model to explore the effects of truncating CYLD mutations on Notch signalling in a disease-relevant cellular context." (PMID 25565632, 2014). "Cylindromatosis was the first described skin cancer caused by mutation in the CYLD gene and subsequent loss of heterozygosity." (PMID 21573132, 2011). "In vivo, CYLD deficient mice were highly sensitive to chemically induced skin tumors and developed significantly larger and faster-growing skin papillomas." (PMID 21573132, 2011). "The presence of aberrant Notch signalling in skin tumours from patients with BSS further supports the hypothesis that the CYLD/MIB2 interaction might play a pathogenic role in human cancer." (PMID 25565632, 2014). "Murine models have been used to investigate the cellular mechanisms behind CYLD-driven skin tumour development." (PMID 37387450, 2023). "All CYLD−/− mice developed skin tumors (papillomas) after 11 weeks vs. only 50–60 % of tumor incidence in CYLD+/+ mice at a later time of 16 weeks." (PMID 31093340, 2016). "Alternatively, CYLD has been shown to be negatively regulated by the Notch and Sonic Hedgehog (Shh) signaling pathways in T-cell leukemia and skin cancer, respectively." (PMID 31093340, 2016). "CYLD has also been shown to play a role in regulating other oncogenic signalling pathways that are relevant in skin tumours, including Wnt and TGF-β signalling." (PMID 25565632, 2014). "Altogether, our results suggest that increased levels of CYLD may be useful for anti-skin cancer therapy." (PMID 34201751, 2021). "These phenomena suggested that copy number variations in the CYLD gene may also be key players and oncogenic drivers in inherited skin tumors." (PMID 32783365, 2020).